BRCA2 (BRCA2 DNA repair associated)
Diseases named in the same sentence as BRCA2 in open-access papers (continued):
Sharing a sentence is not in itself a finding about the gene and the disease.
breast cancer (continued). "Genetic variants in BRCA1 and BRCA2 predispose women to breast and ovarian cancers and are believed to contribute to 5–10% of all breast cancers and 20–40% of familial breast cancers." (PMID 34287743, 2021). "BRCA2, a principal tumor suppressor gene, is involved in DNA damage repair and related to many types of cancer susceptibility, especially breast cancer, and ovarian cancer in adults." (PMID 34367235, 2021). "The same differences between BRCA1 and BRCA2 carriers are also apparent regarding the effect of breastfeeding on breast cancer risk." (PMID 34503502, 2021). "Most women with the BRCA1 mutations who develop breast cancer have triple negative breast cancer, while those with BRCA2 mutations end up with ER+ and/or PR+ forms of breast cancer." (PMID 34171558, 2021). "BRCA1 and BRCA2 are the most commonly mutated breast cancer susceptibility genes that convey a high risk of breast and ovarian cancer." (PMID 34456966, 2021). "According to a study, carriers of BRCA1 and BRCA2 combination, BRCA1, and BRCA2 mutations have a lifetime breast cancer risk of 70%, 24%, and 13%, respectively." (PMID 34376160, 2021). "BRCA1 and BRCA2 genes were identified as genetic risk factors for breast cancer, although mutation carriers represent a minority among breast cancer patients." (PMID 34967927, 2021). "Of the 9 BRCA1 or BRCA2 gene mutated patient carriers, which were examined in this study, a large proportion had experienced a previous breast cancer." (PMID 34209669, 2021). "Overall, germline BRCA1 mutated cancers had significantly higher cyclin E1 protein than the BRCA1 wildtype cases, and tumors with other breast cancer associated germline mutations (BRCA2, PALB2, or CHEK2)." (PMID 34465787, 2021). "Here, we report a case of pathogenic germline BRCA2-driven breast cancer monitored for disease progression and acquired resistance using longitudinal multi-tissue genomic testing." (PMID 33619265, 2021). "Inherited variants in the cancer susceptibility genes, BRCA1 and BRCA2 account for up to 5% of breast cancers." (PMID 34287743, 2021). "Primary prevention measures, including prophylactic mastectomy, chemoprevention, and intensive surveillance, can decrease the risk of breast cancer in BRCA1/BRCA2 mutations." (PMID 34206661, 2021). "Germline mutations in the genes BRCA1 and BRCA2 are known to predispose women to ovarian and breast cancers." (PMID 33750420, 2021). "Breast cancer risk due to loss-of-function variants of PALB2 overlapped with that of BRCA2 variants, validating the direct interaction of PALB2 with BRCA2." (PMID 35008774, 2021). "Breast cancers associated with PALB2 PGVs tended toward phenotypes seen with a BRCA2 PGV, namely both triple negative and high-grade ER-positive HER2-negative tumors." (PMID 34113003, 2021). "In BRCA2 mutation carriers, the cumulative breast cancer risk at the age of 80 years according to these data is increased up to 69% and for ovarian cancer up to 17%, respectively." (PMID 33885953, 2021). "Mutations in BRCA1/BRCA2 are recognized as risk factors for breast cancer induction, but the role in breast cancer prognosis is still controversial." (PMID 34198652, 2021). "BRCA1 and BRCA2 mutations result in 70% risk of developing breast cancer by the age of 80, compared to 12% of the unaffected population." (PMID 34830851, 2021). "The cumulative breast cancer risk for mutation carriers at the age of 70 years is 57% for BRCA1 and 49% for BRCA2 mutation carriers, with a high rate of developing breast cancer." (PMID 34674065, 2021). "Inherited mutations in two different genes (BRCA1 and BRCA2) lead to increased risk of breast cancer." (PMID 34171558, 2021). "BRCA1 and BRCA2 are the most prominent breast cancer susceptibility genes that convey high risk of breast and ovarian cancers." (PMID 34490083, 2021).
breast cancer (continued). "The exome analysis of the BRCA1 and BRCA2 genes in the Amazonian Amerindian populations reported 15 polymorphisms potentially capable of increasing susceptibility to breast cancer." (PMID 33499154, 2021). "Olaparib is an oral medication typically used to treat certain advanced ovarian and breast cancers with mutations in BRCA1 or BRCA2 genes." (PMID 33803939, 2021). "It is well known that monogenic BRCA1 and BRCA2 variants predispose women to breast cancer, but this population is small—perhaps a few per thousand in the general population." (PMID 34440279, 2021). "Cancer survivors harboring inherited pathogenic variants in the breast cancer (BC) susceptibility genes BRCA1 or BRCA2 are at increased risk of ovarian cancer (OC) and also of contralateral BC." (PMID 33466630, 2021). "Women who carry the BRCA1 and BRCA2 germline pathogenic variant (BRCAm) have a high lifetime risk of breast cancer (BC) and ovarian cancer (OC)." (PMID 34356116, 2021). "The prevalence of germline BRCA1 and BRCA2 mutations is 5–15% in breast cancer (BC) and 10–25% of ovarian cancer (OV) patients." (PMID 33525353, 2021). "Heterozygous mutation of BRCA1 and BRCA2 genes alongwith PALB2 contribute to high risk female breast cancer and ovarian cancer." (PMID 34092963, 2021). "HMMR forms a complex with BRCA1 and BRCA2, thus it has been identified as a high-risk factor in multiple cancer types such as breast cancer and fibrosarcoma." (PMID 32241274, 2020). "The major cause is estimated to be the penetrance of the BRCA1 and BRCA2 founder mutation having increased over the last century, as observed by the Collaborative Group on Hormonal Factors in Breast Cancer." (PMID 33180852, 2020). "Because of the fact that among our patients with BRCA1/2 mutations only one had BRCA2 mutation, the results and discussion concern about patients with breast cancer and BRCA1 mutation." (PMID 32322271, 2020). "Their high prevalence in certain breeds suggests a genetic component, as it is the case in human familial breast cancer, distinctly in BRCA2-associated cancers." (PMID 32005245, 2020). "Although only 5 to10% of breast cancer cases in women can be ascribed to BRCA1 or BRCA2 mutations (with BRCA1 mutations slightly more common than BRCA2 mutations), impacts of the gene mutation on carriers is more profound." (PMID 32070378, 2020). "Since the discovery of BRCA1 and BRCA2 genes 25 years ago, several other breast cancer susceptibility genes have been identified." (PMID 32481735, 2020). "BRAF, NRAS, and KIT are three well-known genes associated with melanoma, and BRCA1 and BRCA2 are two representative genes associated with breast cancer." (PMID 33121438, 2020). "Inherited pathogenic variants (PVs) in BRCA1 or BRCA2 genes cause a significantly increased risk for breast cancer (BC), ovarian cancer (OC) and other tumors including pancreas and prostate cancer." (PMID 32380732, 2020). "Biallelic carriers of PVs in other, dominant breast cancer susceptibility genes such as BRCA2, ATM, PALB2, and NBN are known to have more severe cancer phenotypes than monoallelic carriers." (PMID 31993860, 2020). "BRCA1 and BRCA2 mutations are the most prevalent genetic drivers for hereditary breast cancer in humans." (PMID 32850393, 2020). "By the age of 80, the estimated risk for breast cancer for women with germline BRCA1 or BRCA2 mutations is around 80%." (PMID 32053991, 2020). "We have successfully identified a novel, germline heterozygous, missense mutation of the gene BRCA2: c.7007G>T, p.R2336L, which is likely to be pathogenic in the proband and her elder sister who both had breast cancer." (PMID 31782247, 2020). "The odds of a woman who had developed breast cancer exhibiting MF/MC disease were over three times greater if she had a BRCA2 mutation compared to a BRCA1 mutation." (PMID 32022473, 2020). "Breast cancer in men due to a mutation in the BRCA2 gene occurs earlier and with a poorer prognosis." (PMID 32934847, 2020).
breast cancer (continued). "For this, we evaluated the mode of detection in BRCA2 mutation carriers who developed breast cancer while under surveillance." (PMID 32333294, 2020). "In men with BRCA2 mutations, the estimated risk of developing breast cancer is 5% to 10% compared to a risk in the general population of 0.1%." (PMID 32934847, 2020). "In conclusion, we have successfully identified a novel germline heterozygous, likely pathogenic variant of BRCA2: c.7007G>T (p.R2336L) in a Chinese family with breast cancer by NGS‐based genetic diagnosis, enriching its known mutation spectrum." (PMID 31782247, 2020). "Nevertheless, based on the statistics of horizontal pleiotropy, there is a possibility that some genes associated with RA and breast cancer can overlap in the East Asian population and BRCA2 carriers." (PMID 33167385, 2020). "This is in consistence with results from other studies on breast cancer in patients of African ancestry where plausible causal variants in BRCA2 gene were predominant compared to BRCA1." (PMID 32959997, 2020). "In the BRCA2 mutation group, there were 144 breast cancers and seven breast cancer-related deaths among the 739 women in the surveillance cohort (0.1%) and no breast cancers in the mastectomy cohort (n = 406)." (PMID 33238387, 2020). "As a cancer treatment drug, olaparib is first defined as the HR deficient tumor treatment, and it is fully approved by FDA for serous ovarian cancer and breast cancer treatment with germline BRCA1 or BRCA2 mutations." (PMID 32046300, 2020). "The gene contributing most to the inherited breast cancer risk was BRCA2 (P = 3 × 10−10), accounting for 3.7% of the patients, followed by the gene BRCA1 that accounted for an additional 1.6% of the patients (P = 0.01)." (PMID 32318955, 2020). "Another example is for the germline mutations in BRCA1 and BRCA2, in which germline mutation increases risk of hereditary breast cancer." (PMID 33256598, 2020). "We analyzed the association of germline genetic variants with the overall survival after the first primary breast cancer diagnosis in carriers of pathogenic BRCA1 or BRCA2 variants, using Cox regression." (PMID 32964118, 2020). "While hereditary genetic mutations lead to approximately 10 to15% of breast cancer cases, the mutations in BRCA1 and BRCA2 (BRCA) genes are the most penetrating mutations that cause breast cancer." (PMID 32070378, 2020). "In breast cancer, evidence has shown that chemoprevention with tamoxifen reduces the risk of contralateral breast cancer for those women who have variants in the BRCA2 gene." (PMID 31776447, 2020). "The prevalence of pathogenic/likely pathogenic BRCA1/BRCA2 gene mutations among patients with TN disease was 33.9%, and it was 60% among patients with both TN disease and a family history of breast cancer." (PMID 32083950, 2020). "It has been reported that low EZH2 expression, which reduces H3K27 methylation, promoted drug resistance in BRCA-2-deficient breast cancer cells by the regulation of genomic stability." (PMID 31065671, 2020). "A multi-centre prospective cohort of 2272 BRCA1 and 1605 BRCA2 mutation carriers was followed for a mean of 5.4 and 4.9 years, respectively; 426 women developed incident breast cancer." (PMID 31948486, 2020). "Each centre contributed data on clinical presentation, treatment and outcome for breast cancer patients with a known pathogenic BRCA2 variant from their institutions." (PMID 32939053, 2020). "The PRS developed for predicting ER-negative breast cancer showed the strongest association with breast cancer risk for BRCA1 carriers, while for BRCA2 carriers the PRS developed for predicting overall breast cancer risk performed best." (PMID 32665703, 2020). "Breast Cancer: Certain variants in the BRCA1 and BRCA2 genes are known to elevate Breast Cancer risk significantly." (PMID 32694572, 2020).
breast cancer (continued). "Among these genes, BRCA1 and BRCA2, as well-known tumor suppressor genes, were associated with breast cancer risk, which was identified from 1994 to 1995." (PMID 32879886, 2020). "We found 7 mutations in the BRCA2 gene (3 of which are located in exon 10 and 4 in exon 11), of which 1342A>G has been shown to be associated with breast cancer and ovarian cancer." (PMID 32356124, 2020). "Detection of a pathogenic BRCA2 mutation (c.5159C>A; S1720∗), in 1/13 (8%) of the breast cancer patients with familial breast cancer confirmed that family history is an important indicator for the diagnosis of inherited breast cancer in Kenya." (PMID 32231682, 2020). "Genetic testing was performed on her two cousins with breast cancer who carried a BRCA2 gene with the same pathogenic variant." (PMID 32806537, 2020). "Published studies to date suggest that the breast cancer risk in PHTS is similar to that in women with germline PVs in BRCA1/BRCA2." (PMID 32533092, 2020). "Cells expressing these two breast cancer variants in a BRCA2 deficient background display defective chromosome congression to the metaphase plate due to a reduced microtubule–kinetochore stability, causing a substantial delay in mitosis progression." (PMID 32286328, 2020). "BRCA2 variant identified in the patient was previously published and considered predisposing for breast cancer." (PMID 31937788, 2020). "Adjustment for oestrogen receptor status gave odds of a BRCA2 mutation carrier developing MF/MC breast cancer 4.2 times greater than a BRCA1 mutation carrier (CI: 2.12–8.19) (p < 0.001)." (PMID 32022473, 2020). "Joint modeling of both monogenic variant status and polygenic score estimated that the risk for breast cancer among carriers of a BRCA1 or BRCA2 variant ranges from 1.43-fold to 16.68-fold increased risk across percentiles of the polygenic score." (PMID 32820175, 2020). "Germline pathogenic variants in BRCA1 and BRCA2 increase cumulative lifetime risk up to 75% for breast cancer and 76% for ovarian cancer." (PMID 33081408, 2020). "According to our selection criterion of variants, 20 potentially pathogenic variants containing 9 variants in BRCA1 and 11 variants in BRCA2 were detected in at least one case from 70 familial breast cancer cases." (PMID 32879886, 2020). "In this work, we described a novel BRCA2 splice variant identified in a 33‐year‐old breast cancer patient belonging to a HBOC family." (PMID 33159495, 2020). "In this multicenter study, the screening results in BRCA2 mutation carriers showed a high screening sensitivity of 95.2% as well as a high percentage of early-stage breast cancer (68.2%) and a very low fraction of interval cancers (4.7%)." (PMID 32333294, 2020). "The method reveals that ESR1, FGFR2, VDR, CNTNAP2, and BRCA2 have a weak association with sporadic breast cancer in the Uruguayan population." (PMID 33126731, 2020). "The prevalence of MF/MC disease was 13.3% amongst BRCA1 mutation carriers diagnosed with breast cancer, and 47.1% amongst BRCA2 mutation carriers diagnosed with breast cancer." (PMID 32022473, 2020). "From January 2003 to March 2019, 83 BRCA2 mutation carriers were diagnosed with 85 breast cancers while under surveillance with both MRI and digital mammography." (PMID 32333294, 2020). "The object of the trial is to evaluate the presence or disappearance of cytological atypias and the level of biomarkers characteristic for breast cancer in healthy women with BRCA1 or BRCA2 gene mutation or in premenopausal women." (PMID 32471217, 2020). "Together, mutations in the BRCA1 and BRCA2 genes contribute to about 20–25% of inherited breast cancers." (PMID 32824813, 2020). "The OlympiAD trial, which was the global phase 3 trial for metastatic HER2-negative breast cancer with germline BRCA1 or BRCA2 mutations, confirmed that olaparib increased PFS by 2.8 months to 7.0 months (hazard ratio 0.58; P<0.001) and received FDA approval." (PMID 32046300, 2020).
breast cancer (continued). "The “Korean Hereditary Breast Cancer Study” showed that soy intake was associated with a lower risk of breast cancer in BRCA mutation carriers (especially BRCA2 mutations)." (PMID 32085420, 2020). "Here we describe a novel variant at the highly conserved splice consensus site in BRCA2 intron 8, identified in a young woman affected with breast cancer and belonging to a HBOC family." (PMID 33159495, 2020). "Hereditary breast cancer can account for 5 to 10% of all breast cancer patients, and BRCA1/BRCA2 mutations can be detected in more than 60% of hereditary breast cancer patients." (PMID 32944243, 2020). "Roughly, 70% breast cancers evolving in BRCA1 mutation carriers while 23% of breast cancers evolving in BRCA2 carriers, express a triple negative phenotype." (PMID 32245065, 2020). "In this article, we describe a novel c.682‐2delA splice variant of BRCA2, identified in an early onset breast cancer proband belonging to a HBOC family." (PMID 33159495, 2020). "Knowledge of germline BRCA1 or BRCA2 variant status results in increased breast cancer surveillance, earlier breast cancer diagnosis, increased gynecological cancer surveillance, and prevention of fallopian tube and ovarian cancers." (PMID 32028617, 2020). "In BRCA2 mutation carriers of 50 years and older, mammographic screening contributed significantly in the detection of early-stage breast cancer." (PMID 32333294, 2020). "The BARD1 protein structure is like that of the BRCA1, however it is different from that of the BRCA2 (BReast CAncer type 2), the second gene associated with breast cancer." (PMID 33114377, 2020). "A plausible explanation is that the Uruguayan population is the most aged in South America, and BRCA2 mutations are slightly more common between older women with sporadic breast cancer." (PMID 33126731, 2020). "The inheritance of mutated BRCA1 or BRCA2 alleles results in a lifetime risk of breast cancer as high as 80%." (PMID 33257598, 2020). "Intuitively, it would seem that women with a BRCA1 mutation would most likely be the ones to consider BPM as they have a higher breast cancer risk than BRCA2 mutations." (PMID 31832891, 2020). "Although approximately 12% of women in general population develop breast cancer all through their life, 72% of women with pathogenic BRCA1 mutation and 69% of women with pathogenic BRCA2 mutation are diagnosed with breast cancer at a stage of life." (PMID 33488844, 2020). "They suggest that the high risk of contralateral breast cancer in BRCA1/BRCA2 mutation carriers must be taken into account when choosing treatment." (PMID 33019612, 2020). "The risk of breast cancer and ovarian cancer in BRCA2 mutation carriers is 50~85% and 10~20%, respectively." (PMID 32356124, 2020). "In this multicenter study, proven BRCA2 mutation carriers, who developed breast cancer during screening using both digital mammography and state-of-art breast MRI, were identified." (PMID 32333294, 2020). "In support, a polymorphism in the 5′UTR of Brca2 that decreases the secondary structure and promotes translation is protective against breast cancer in patients." (PMID 32681145, 2020). "BRCA1 and BRCA2 genes are found to be strongly associated with breast cancer and the frequency of these genetic mutations varies among ethnic groups and countries." (PMID 32856854, 2020). "Breast cancers arising in women with a BRCA1 or BRCA2 germline mutation are characterized by genomic instability." (PMID 32711554, 2020). "There is a well-documented association between women carrying pathogenic germline mutations in breast cancer gene one (BRCA1) or breast cancer gene two (BRCA2) and their risk of developing ovarian cancer." (PMID 32098980, 2020). "For example, two well-known cancer genes, BRCA1 and BRCA2, were the major genes associated with the genetic etiology of breast cancer." (PMID 32802855, 2020).